UBL7 (ubiquitin like 7)
Description:
Interferon-stimulated protein that positively regulates RNA virus-triggered innate immune signaling. Mechanistically, promotes 'Lys-27'-linked polyubiquitination of MAVS through TRIM21 leading to enhanced the IFN signaling pathway.
Synonyms: BMSC-UbP; MGC14421; TCBA1
Tractability: PROTAC: ubiquitination databases record sites on it; its protein half-life has been measured.
Gene: Protein-coding gene on chromosome 15 (74,445,187 to 74,461,182, reverse strand). Ensembl gene ENSG00000138629.
Subcellular location (Human Protein Atlas): Nucleoplasm; Cytosol
Gene Ontology:
Molecular function: protein binding; protein-macromolecule adaptor activity
Biological process: antiviral innate immune response; ubiquitin-dependent protein catabolic process
Cellular component: cytoplasm
Genetic constraint (gnomAD): Loss-of-function variants: 21 observed, 40.29 expected, observed/expected ratio (o/e) 0.52, 90% interval 0.37 to 0.75. The upper end of that interval is the gene's LOEUF score, 0.75, which puts it in group 3 of 6, group 1 being the genes least tolerant of losing a copy. Missense variants: 403 observed, 485.98 expected, observed/expected ratio (o/e) 0.83, 90% interval 0.76 to 0.9. Synonymous variants: 157 observed, 190.42 expected, observed/expected ratio (o/e) 0.82, 90% interval 0.72 to 0.94.
Homologues: Orthologues: chimpanzee UBL7 (99% identical), macaque UBL7 (99% identical), mouse Ubl7 (98% identical), rat Ubl7 (98% identical), guinea pig UBL7 (97% identical), pig UBL7 (97% identical), dog UBL7 (87% identical), rabbit UBL7 (80% identical), tropical clawed frog ubl7 (72% identical), zebrafish ubl7a (71% identical), zebrafish ubl7b (59% identical), Drosophila melanogaster CG31528 (14% identical). Paralogues in human: UBQLN1 (28% identical), UBQLN2 (28% identical), UBQLN4 (26% identical), UBQLN3 (23% identical), UBQLNL (12% identical).